TACC3 (transforming acidic coiled-coil containing protein 3)
Diseases named in the same sentence as TACC3 in open-access papers (continued):
Sharing a sentence is not in itself a finding about the gene and the disease.
breast tumor (5 papers, 2005 to 2023). "In our METABRIC eQTL analysis of breast tumor data, SNPs correlated with rs798755 were associated with the expression of TACC3 (p = 0.00099)." (PMID 28179588, 2017). "Our breast tumor eQTL and target prediction analyses pointed to TACC3 as the gene most likely affected by variants in this region." (PMID 28179588, 2017). "This would be consistent with the association of the rs798755 minor allele with high TACC3 expression in our eQTL analysis of breast tumor data." (PMID 28179588, 2017). "Altogether, our results show that TACC3 is a multifunctional driver of highly aggressive breast tumors with CA and that targeting TACC3 is a promising approach to tackle this disease." (PMID 36864125, 2023). "We examined the expression of TACC3 between breast tumors and adjacent normal tissues using the DriverDBv3 database." (PMID 34149795, 2021). "Indeed, in a survey of 500 resected breast tumors, TACC3 protein was significantly reduced in approximately 50% of the tumors." (PMID 15918899, 2005). "Notably, in another patient cohort (Hacettepe cohort) which has follow up data, we demonstrated that high TACC3 protein expression is significantly associated with worse overall survival in TNBC subtype, further supporting the role of TACC3 in highly aggressive breast tumors with CA." (PMID 36864125, 2023).
head and neck cancer (5 papers, 2014 to 2025). A primary or metastatic malignant neoplasm affecting the head and neck. "We describe nine FGFR3::TACC3 fusion–positive head and neck carcinomas affecting six males and three females aged 38 to 89 years (median, 59)." (PMID 39387893, 2025). "We herein describe nine head and neck carcinomas identified in our files carrying the FGFR3::TACC3 fusion in an attempt to characterize their morphological spectrum." (PMID 39387893, 2025). "Our current series is the first one devoted to morphological characterization of head and neck carcinoma harboring the FGFR3::TACC3 fusion." (PMID 39387893, 2025). "In summary, we described a series of nine head and neck carcinomas carrying an FGFR3::TACC3 fusion." (PMID 39387893, 2025). "However, the morphology of FGFR3::TACC3-positive head and neck carcinomas has not been well studied and it is unclear if this fusion represents a random event, or if it might characterize a morphologically distinct tumor type." (PMID 39387893, 2025).
leukemia (5 papers, 2005 to 2025). A malignant (clonal) hematologic disorder, involving hematopoietic stem cells and characterized by the presence of primitive or atypical myeloid or lymphoid cells in the bone marrow and the blood. "To determine whether ALKBH5-mediated regulation of energy metabolism is required for leukemogenesis in addition to reduction of TACC3 and AXL1 to limit AML survival, we generated Mll-AF9 mutant leukemia from Cre-rtTA-Alkbh5fl/fl mice." (PMID 37742191, 2023).
cervical squamous cell carcinoma (4 papers, 2013 to 2021). A squamous cell carcinoma arising from the cervical epithelium. "Consistently, TACC3 mRNA expression was was not markedly increased in N0 cervical squamous cell carcinoma (CESC) tissues compared with N1 CESC tissues from The Cancer Genome Atlas (TCGA) dataset." (PMID 34134633, 2021).
esophageal cancer (4 papers, 2016 to 2024). A primary or metastatic malignant neoplasm involving the esophagus. "Among our methylation signatures, some genes have been reported in the onset and progression of BE and esophageal cancer or the prognosis of esophageal cancer, such as TRIM15, TACC3, SHANK2, and MCC." (PMID 31834866, 2019).
rectal cancer (4 papers, 2018 to 2025). A primary or metastatic malignant neoplasm that affects the rectum. "Our results indicate that rectal cancer patients overexpressing TACC3 were more likely to experience CRT resistance [risk ratio (RR) = 2.236, 95% confidence interval (CI): 1.447–3.456; P = 0.001]." (PMID 30341253, 2018). "TACC3 overexpression is related to chemoradiotherapy resistance in patients with locally advanced rectal cancer." (PMID 31546954, 2019). "Transforming acidic coiled-coil protein-3 (TACC3) is frequently aberrantly expressed in rectal cancer tissue." (PMID 30341253, 2018). "In the present study, therefore, we used biopsy samples from rectal cancer patients and colorectal cell lines to assess the relationship between TACC3 expression and CRT sensitivity." (PMID 30341253, 2018). "Additionally, a study on locally advanced rectal cancer found that knockout TACC3 enhanced the inhibition of HCT116 and SW480 cell proliferation and colony formation induced by irradiation, while increasing radiation-induced apoptosis." (PMID 40402389, 2025). "The expression of TACC3 may predict the radiosensitivity and prognosis of locally advanced rectal cancer." (PMID 34149795, 2021). "This highlights TACC3 as a significant factor influencing overall survival (OS) and progression-free survival (PFS) in rectal cancer." (PMID 40402389, 2025). "Approximately 21.05% of rectal cancer patients did not express TACC3, while 7.24% of rectal cancer patients exhibited strong expression of TACC3." (PMID 30341253, 2018). "Our results indicate that higher TACC3 expression is strongly related to poorer disease-free survival (P = 0.032) and that rectal cancer patients not expressing TACC3 tend to have better overall survival, though the difference is not significance (P = 0.072)." (PMID 30341253, 2018).
esophageal squamous cell carcinoma (3 papers, 2015 to 2017). Esophageal squamous cell carcinoma (ESCC) is a type of esophageal carcinoma (EC) that can affect any part of the esophagus, but is usually located in the upper or middle third. "In a study of esophageal squamous cell carcinomas, however, the cut-off value for high TACC3 expression was determined by the immunoreactivity score, product of the staining intensity, and percentage of positive cells; moreover, the rationale behind the selected cut-off value was not stated." (PMID 29135996, 2017).
ganglioglioma (3 papers, 2024 to 2025). A well differentiated, slow growing neuroepithelial neoplasm composed of neoplastic, mature ganglion cells and neoplastic glial cells. "Although ganglioglioma may harbor mutations or fusions of FGFR genes, FGFR3::TACC3 fusion has not been observed in any tumor with histological features of ganglioglioma." (PMID 38730596, 2024).
pancreatic cancer (3 papers, 2020 to 2024). "That is, abnormally low expression of Lnc-PCTST in pancreatic cancer leads to high expression of TACC3, which promotes the proliferation and invasion ability of cancer cells." (PMID 38012214, 2023). "TACC3 expression varied across pancreatic cancer cell lines, with the highest expression in Panc-1 cells." (PMID 38012214, 2023). "To select suitable cell lines for in vitro experiments, we evaluated the abundance of TACC3 in established human pancreatic cancer cell lines, including the SW1990, BxPC-3, Mia-PaCa-2, Capan-1, CFPAC-1, and Panc-1 cell lines, by Western blotting and qPCR." (PMID 38012214, 2023). "Therefore, we used Panc-1 cells, which had the highest TACC3 expression, to investigate the function of TACC3 in pancreatic cancer cells." (PMID 38012214, 2023).
thyroid cancer (3 papers, 2010 to 2020). "However, the downregulation of TACC3 expression was detected in ovarian and thyroid cancers." (PMID 29088887, 2017). "However, TACC3 expression is reduced in ovarian and thyroid cancer." (PMID 21113414, 2010).
triple-negative breast carcinoma (3 papers, 2021 to 2025). An invasive breast carcinoma which is negative for expression of estrogen receptor (ER), progesterone receptor (PR), and human epidermal growth factor receptor 2 (HER2). "Previous studies have also reported differing responses of the two triple negative breast cancer cell lines to TACC3 inhibitors, which may reflect distinct functional interactions of TACC3 throughout￼." (PMID 40585227, 2025). "To probe this, we selected two triple-negative breast cancer (TNBC) cell lines (MDA-MB-468 and MDA-MB-231) in which to apply the TACC3 stapled peptides." (PMID 40585227, 2025).
primary immunodeficiency (2 papers, 2021). "Gene sets differentially enriched in the high TACC3 expression phenotype included many genes related to immunomodulation, such as autoimmune thyroid disease, cytokine-cytokine receptor interaction, primary immunodeficiency, NK cell-mediated cytotoxicity, and antigen processing and presentation." (PMID 33714201, 2021).
renal cell carcinoma (2 papers, 2017 to 2021). "Knockdown of TACC3 inhibited the proliferation, invasion and tumorigenesis in renal cell carcinoma (RCC) cells." (PMID 29088887, 2017). "However, the expression pattern and roles of TACC3 in renal cell carcinoma still remain unclear." (PMID 33714201, 2021).
soft tissue sarcoma (2 papers, 2017 to 2022). A malignant neoplasm arising from muscle tissue, adipose tissue, blood vessels, fibrous tissue, or other supportive tissues excluding the bones. "However, the relationship between TACC3 and soft tissue sarcomas (STS) remains unclear." (PMID 29135996, 2017).
Alzheimer disease (1 paper, 2022). A progressive, neurodegenerative disease characterized by loss of function and death of nerve cells in several areas of the brain leading to loss of cognitive function such as memory and language. "Among them, 8 KEGG pathways illustrated positively correlated with TACC3 expression: pathways of neurodegeneration-multiple diseases, Alzheimer disease, oocyte meiosis, phagosome, cell cycle, cellular senescence, DNA replication, and progesterone-mediated oocyte maturation." (PMID 35855850, 2022).
bladder (1 paper, 2017). "Fibroblast growth factor receptor 3–transforming acidic coiled-coil containing protein 3 (FGFR3–TACC3; FT3) is a gene fusion resulting from rearrangement of chromosome 4 that has been identified in many cancers including those of the urinary bladder." (PMID 28855393, 2017).
cervical tumor (1 paper, 2017). "Recent researches have suggested that TACC3 is able to regulate epithelial-mesenchymal transition (EMT) of cervical tumor cells." (PMID 29088887, 2017).
clear cell carcinomas (1 paper, 2005). "The distribution pattern of expression of the two TACC proteins was different, with TACC3 loss being more common in serous papillary carcinoma compared with clear cell carcinomas, while TACC1 staining was less frequent in endometroid than in serous papillary tumor cores." (PMID 15918899, 2005).
clear cell ovarian tumor (1 paper, 2005). "TACC3 expression was observed in 21.4% (9 of 42) serous papillary, 40% (2 of 5) mucinous, 42.8% (3 of 7) endometroid, and 63.6% (7 of 11) clear cell ovarian tumor cores." (PMID 15918899, 2005).
ependymoma (1 paper, 2025). A WHO grade II, slow growing tumor of children and young adults, usually located intraventricularly. "Supratentorial ependymomas in adults can mimic diffuse gliomas with FGFR3::TACC3 fusion when displaying infiltrative growth." (PMID 40417325, 2025).
familial ovarian cancer (1 paper, 2005). An instance of ovarian cancer that is caused by an inherited modification of the individual's genome. "As the TACC3 gene is located within 4p16, we next investigated whether constitutional mutations occur within the TACC3 gene in familial ovarian cancer." (PMID 15918899, 2005).
Fanconi anemia (1 paper, 2025). Fanconi anemia (FA) is a hereditary DNA repair disorder characterized by progressive pancytopenia with bone marrow failure, variable congenital malformations and predisposition to develop hematological or solid tumors. "Six hub genes (FANCI, KAT2A, TACC3, TPX2, VHL, WSB1) were enriched in Fanconi anemia and HIF-1 pathways, affecting microtubules, spindle formation, and cytoskeleton dynamics during mitosis." (PMID 40832468, 2025).
intestinal tumors (1 paper, 2022). "TACC3 deletion was found to suppress the growth of intestinal tumors in vitro and in vivo by perturbing the mitotic spindle of intestinal stem cells." (PMID 36221072, 2022).
mesothelioma (1 paper, 2025). A usually malignant and aggressive neoplasm of the mesothelium which is often associated with exposure to asbestos. "By intersecting high-risk genes with upregulated DEGs, we identified four key high-risk genes associated with mesothelioma: MPZL1, SOAT1, TACC3, and CYBRD1." (PMID 40223054, 2025). "Additionally, we discovered that the genes SOAT1, TACC3, and NDRG2 are linked to the prognosis of mesothelioma patients." (PMID 40223054, 2025). "Currently, there are no research reports on the roles of SOAT1, TACC3, and NDRG2 in mesothelioma." (PMID 40223054, 2025).
metastatic tumor (1 paper, 2016). "The metastatic tumor showed FGFR3-TACC3 fusion (break point intron 17 and TACC3 intron 10)." (PMID 27409839, 2016).
nasopharyngeal tumors (1 paper, 2025). "Except for the nasopharyngeal tumors and the multiphenotypic sinonasal carcinomas, the vast majority of FGFR3::TACC3-positive reported cases were supposed to have represented SCC." (PMID 39387893, 2025).
ovarian tumor (1 paper, 2005). "This study demonstrated absence of at least one or both TACC proteins in 78.5% (51/65) of ovarian tumors tested, with TACC3 loss observed in 67.7% of tumors." (PMID 15918899, 2005). "Recent, large-scale genomic analysis and Serial Analysis of Gene Expression data suggest that TACC1 and TACC3 may also be involved in the etiology of ovarian tumors from both familial and sporadic cases." (PMID 15918899, 2005). "In particular, we have determined that 67.7% (44 of 65) of ovarian tumors lose expression of TACC3." (PMID 15918899, 2005). "Furthermore, TACC3 is downregulated in all 7 of the bulk ovarian tumors and tumor cell lines, compared with the normal human ovarian surface epithelium (HOSE)." (PMID 15918899, 2005). "We have now shown that 78.5% of ovarian tumors lack appreciable expression of TACC1 and/or TACC3 proteins, confirming the inferences made from published SAGE analysis." (PMID 15918899, 2005). "Within the ovarian tumor set tested (n = 65), there was a significant difference in the expression of TACC1 compared to TACC3 (Fisher's exact test, p = 0.0008)." (PMID 15918899, 2005). "Intriguingly, similar to TACC3, two members of this latter family, GATA 4 and GATA 6, are either lost or mislocalized in ovarian tumors." (PMID 15918899, 2005). "This has revealed that 78.5% of ovarian tumors lack appreciable expression of TACC1 and/or TACC3." (PMID 15918899, 2005).
salivary gland carcinoma (1 paper, 2025). A carcinoma that arises from the major or minor salivary glands. "The FGFR3::TACC3 fusion has been reported in one of 27 metastatic salivary gland carcinomas subjected to next-generation sequencing in one study." (PMID 39387893, 2025).
schizophrenia (1 paper, 2023). A major psychotic disorder characterized by abnormalities in the perception or expression of reality. "Studies have shown that centriolar coiled-coil protein 110 (CCP110), cytoskeleton-associated protein 5 (CKAP5), disrupted in schizophrenia 1 (DISC1), and transforming acidic coiled-coil containing protein 3 (TACC3) are essential for oocyte microtubule polymerization and spindle assembly." (PMID 37240406, 2023).
thymoma (1 paper, 2021). A neoplasm arising from the epithelial cells of the thymus. "Overexpression of TACC3 is associated with poor prognosis only in KIRC, liver hepatocellular carcinoma and thymoma." (PMID 33714201, 2021).
cancer (117 papers, 2005 to 2025). A tumor composed of atypical neoplastic, often pleomorphic cells that invade other tissues. "TACC3 overexpression is associated with poorer clinical outcomes compared to lower expression levels in various cancers, including breast, ovarian, lung, and gastric." (PMID 39603208, 2025). "Overall, high TACC3 expression is associated with tumor aggressiveness and poor prognosis across multiple cancer types, highlighting its potential as a prognostic or therapeutic biomarker." (PMID 39603208, 2025). "SP TACC3 efficiently penetrates cells and displaces TACC3 from the mitotic spindle, causing a delay in mitotic progression in two out of three cancer cell lines." (PMID 40585227, 2025). "Transforming acidic coiled-coil 3 (TACC3), a centrosome- and microtubule-associated protein, is frequently overexpressed and strongly linked to cancer progression and metastasis across multiple malignancies." (PMID 40246827, 2025). "High TACC3 expression is linked to tumor aggressiveness and poor survival across various cancers, underscoring its potential as a biomarker." (PMID 39603208, 2025). "Transforming acidic coiled-coil 3 (TACC3) is upregulated in solid tumors and strongly associated with worse prognosis in several different cancers, such as breast, lung and ovarian cancer." (PMID 36864125, 2023). "Subsequently, we explored the association between TACC3 expression and ICP genes in human cancers to explore the potential of TACC3 in immunotherapy." (PMID 35855850, 2022). "Next, we assessed an additional imperative aspect, since the TACC3 expression is associated with numerous recognized pathways in the immune responses and cancer processes." (PMID 35855850, 2022). "Among the 47 ICP genes, multiple cancer types closely associated with TACC3 expression were found, such as KICH, KIRC, THCA, THYM, CHOL, DLBC, ACC, and UVM." (PMID 35855850, 2022). "Yet, overexpressed ALHBK5 up-regulates critical target TACC3, a prognosis-associated oncogene in various cancers, to selectively promote tumorigenesis and cancer stem cell self-renewal in acute myeloid leukemia." (PMID 35093087, 2022). "TACC3 encodes a member of the acidic Escherichia coli chain protein family, which plays a role in the differentiation and growth of certain cancer cells." (PMID 34381020, 2021). "Overexpression of TACC3 is associated with poor prognosis in the breast, prostate and colorectal cancers." (PMID 33796525, 2021). "As TACC3 is intimately linked to cancer, it will also be interesting in future to investigate the possible link of TACC3-mediated γ-tubulin complex stabilization and astral microtubule assembly with tumorigenesis." (PMID 31823729, 2019). "In summary, the overexpression of TACC3 is significantly associated with poor survival in patients with various types of cancer." (PMID 29088887, 2017). "Our results clearly indicate that the reduced level of TACC3 at the mitotic spindle is the cause of mitotic problems in FT3-positive cancer cell lines and that this reduction is due to a TACC3-specific function of FT3." (PMID 28855393, 2017). "TACC3 is a cancer-associated protein belonging to the TACC family, and is important for mitotic spindle stability." (PMID 28855393, 2017). "Genetic variations on chromosome 4p16.3, the region encoding TACC3, are found in various human cancers." (PMID 23936413, 2013). "However, only 2/7 (29%) carcinomas with FGFR3::TACC3 fusion (excluding a case with concomitant FGFR3 mutation) had elevated FGFR3 mRNA expression." (PMID 39596194, 2024).